CD68 (CD68 molecule)
Diseases named in the same sentence as CD68 in open-access papers (continued):
Sharing a sentence is not in itself a finding about the gene and the disease.
tumor (continued). "Importantly, CD11b/CD68 positive cells were observed surrounding the tumors cells in fallopian adenocarcinoma and in EOC, suggesting these cells may represent tumor associated macrophages (TAMs)." (PMID 25971554, 2015). "The expression of CD68 (all macrophages, DCs, and neutrophils) tended to be higher than that of CD163 (pro-tumor macrophages)." (PMID 26374556, 2015). "It is of note, however, that tumor microenvironment including elevated CD8+ T cells, forkhead box protein 3 (FoxP3)+ T cells, and CD68+ macrophages can also contribute to the downgrading of bone marrow FL." (PMID 25815348, 2015). "This could be performed routinely in the scope of microscopical histological tumor evaluation as well as in standardized and reliable protocols on paraffin-embedded tumor specimens after staining with commercially available and commonly used antibodies against the macrophage marker CD68." (PMID 26497197, 2015). "Peritumoral IL-6, IL-6R, gp130, CD68, and HIF-1α expression, as well as MVD, gradually increased during tumor growth." (PMID 26525581, 2015). "Quantification of staining in tumor tissues showed that 97% of GFP+ cells in control tumors also expressed CD45, 85% expressed CD11b, 62% expressed F4/80, and approximately 47% were CD68+." (PMID 26418962, 2015). "Analysis of the immune infiltrate in post-chemotherapy residual tumor identified a profile (cluster Y), mainly characterized by high CD3 and CD68 infiltration, with a worse disease free survival." (PMID 25432519, 2014). "The total number of macrophages (CD68+ cells) was similar in tumoral and normal surrounding tissue, but the number of M2 macrophages (CD206+ cells) was significantly higher in the tumor." (PMID 24901518, 2014). "DTCs were detected using immunocytochemistry, the level of tumor hypoxia using NMR spectroscopy, CD68, CD34, VEGF, and VEGFR-1 (Flt-1) expression using immunohistochemistry, and MMP-2 and MMP-9 activity using zymography." (PMID 24669218, 2014). "viii) A high abundance of fibroblasts (L1) in the tumoral stroma correlated with increased L1CAM expression in the carcinoma cells (P2) and high numbers of CD68+ (H1) and CD163+ (I1) macrophages correlated with elevated vimentin expression in tumor cells (R)." (PMID 24797069, 2014). "At low numbers, CD68+ (H1) and CD163+ (I1) macrophage predominantly localized close to tumor cells while at higher numbers, both macrophage populations were equally distributed throughout the tissues, respectively (H2,I2)." (PMID 24797069, 2014). "CD8 positive T-cells and the total macrophage count, using the CD68 pan-macrophage marker, and CD163 positive M2 macrophage count were determined in tumor specimens prior to treatment." (PMID 25192022, 2014). "RUNX1 was associated with progesterone receptor (PR)-positive tumours (P<0.05), more tumour CD4+(P<0.05) and CD8+(P<0.01) T-lymphocytic infiltrate, increased tumour CD138+plasma cell (P<0.01) and more CD68+macrophage infiltrate (P<0.001)." (PMID 24967588, 2014). "Results showed that most tumor tissues had higher densities of CD163+ and CD68+ macrophages infiltration than those in the tumor-free tissues." (PMID 25144454, 2014). "Meanwhile, many CD68-positive cells were also found, but there were only a few large CD30-positive and CD1α-positive cells in the tumor tissue." (PMID 25273521, 2014). "We found abundant macrophages in the stroma of the tumor tissue which showed both TREM-1 and CD68 expressions." (PMID 24842612, 2014). "Immunostaining showed that the tumor was positive for the Vimentin, Desmin and MyoD1, and was negative for CK, P63, NSE, CD45, CD30, S-100, CD99, Myoglobin, CD68, CD34, CD31, and α–SMA." (PMID 23379991, 2013). "We therefore evaluated the number of CD68 and CD163 positive macrophages in the tumor microenvironment using IHC analysis." (PMID 24236041, 2013).
tumor (continued). "Immunostaining showed that the tumor was strongly positive for Vimentin, Desmin and MyoD1, and was negative for CK, P63, NSE, CD45, CD30, S-100, CD99, Myoglobin, CD68, CD34, CD31, α–SMA." (PMID 23379991, 2013). "CD68 and CD163 staining appeared mainly in the cytoplasm of stroma cells in tumor and peritumoral liver tissue." (PMID 23555776, 2013). "The numbers of CD68-positive macrophages and Iba-I-positive microglia in the SDFkd tumors were lower (20% and 38%, respectively) than those in the irradiated ALTS1C1 tumor." (PMID 23940516, 2013). "Dual immunofluorescence staining revealed that the expression of TIM-3 was observed in all cell types investigated, including CD68+ macrophages, CD31+ endothelial cells, CK-18+ epithelial cells and PCNA+ tumor cells." (PMID 24137353, 2013). "The densities of CD68+ and CD163+ cells in peritumoral liver tissue were significantly higher than those within tumor (P<0.001 for both)." (PMID 23555776, 2013). "In this study, the distribution and clinical significance of macrophages in tumor and peritumoral liver tissues were evaluated with the markers of CD163 and CD68, and the differences between these two markers were analyzed." (PMID 23555776, 2013). "We have used such a platform to develop a novel technique, namely double-labelling immunostaining of MGMT and a "cocktail" of non-tumour antigens (CD34, CD45 and CD68)." (PMID 24252243, 2013). "To investigate the potential role of HIF-2α in carcinoma, we first examined its expression and distribution in serial sections of human HCC tumor samples stained for HIF-2α and CD68 (marker for monocytes/macrophages)." (PMID 24194900, 2013). "The tumor cells are immunoreactive for S-100 proteins, calretinin, NSE, laminin and CD68 (Kp1), but they do not react with antibodies for neurofilaments or glial fibrillary acidic protein (GFAP)." (PMID 24349953, 2013). "Immunohistochemistry was used to evaluate the expression of CD68, M-CSF, CSF-1R, CD57, TGF-beta and Ki67 in tumor and peritumoral capsule." (PMID 22554285, 2012). "Tumour deposits from the omentum of HGSC patients contained a prominent leukocyte infiltrate of CD3+ T cells and CD68+ macrophages, with occasional neutrophils." (PMID 22322968, 2012). "The degree of inflammation measured by the expression of CD68 and CD45 showed a positive significant correlation with tumor size and tumor growth index." (PMID 22555941, 2012). "In concordance with the murine data, the NSCLC study revealed a positive, significant correlation between CD68+ macrophage density, intraepithelial TGF-β levels and expression of EMT markers in adjacent tumor cells." (PMID 22273460, 2012). "It has been also recently demonstrated that high level of CD68 correlated with poorer survival, event-free survival, and with the presence of EBV in the tumor cell population." (PMID 22927872, 2012). "Both evaluations established a moderate, positive correlation between intratumoral CD68+ macrophage density, mesenchymal marker expression and TGF-β1 levels in tumor cells (SC > 0.2)." (PMID 22273460, 2012). "This analysis identified local correlations between tumor cell expression of EMT markers and intratumoral CD68+ macrophage density." (PMID 22273460, 2012). "It is known that CD11b+ tumor-associated macrophages (TAM) mainly express genes of the M2 type such as CD68, F4/80 and VEGFR-1, and is actively involved in tumor invasion and progression." (PMID 21481239, 2011). "High tumour stage (TNM) was predictive for poor survival, while CD68 and Gas6 protein expression correlated with a favourable outcome." (PMID 21794149, 2011). "We found that lower levels of CD3ε, CD25, CD68, and ICAM-1 mRNA in BCC tumor biopsies at baseline predicted subsequent BCCs." (PMID 21980389, 2011). "The tumor also expresscs Vimentin, PGP9.5, NKI/C3, and CD68 while some markers such as Inhibin-α, Calretinin, Galectin-3, and HBME show varying rates of staining." (PMID 22132340, 2011).
tumor (continued). "Tumor cells demonstrated positive staining for the follicular dendritic cell markers CD21 (49/49), CD35 (43/45), CD23 (20/23), CD68 (23/25), Vimentin (22/28), and 18 cases showed immunostaining for S-100 protein." (PMID 20937101, 2010). "Consistently, infiltration of the tumor by both CD3 and CD68 cells was significantly more frequent in responders to radiotherapy than in non-responders." (PMID 20822523, 2010). "Applying robust backward selection in a nested cross-validated fashion resulted in a highly compact model consisting of five variables: AURKA, tumor size, HER2, CD68 and nuclear grade." (PMID 20809974, 2010). "Tumor cells demonstrated positive staining for the follicular dendritic cell markers CD21 (47/49), CD35 (43/45), CD23 (20/23) and CD68 (23/25)." (PMID 20937101, 2010). "Immunohistochemical quantification (score 0-3) was performed for CD3, CD4, CD8, CD45RO, CD68, CD163, FoxP3, GranzymeB, iNOS, mast cell tryptase, MUM1, PD1 and TIA-1 tumor-infiltrating (TILs) reactive cells." (PMID 21179245, 2010). "The tumor showed strong positive staining (with membrane enhancement) for PLAP, CD117 and CD68, focal positivity for MNF116, while the balance of antibodies were negative." (PMID 19642973, 2009). "Tumour-infiltrating immune cells were identified using antibodies specific for CD3, CD8, GranzymeB, FoxP3, CD20 and CD68 and quantified using an image analysis system." (PMID 19698134, 2009). "The infiltration of the primary tumour by CD3+, CD8+, CD20+, CD68+ and Granzyme B+ had only limited influence on DFS." (PMID 19698134, 2009). "By immunohistochemistry, the tumour was positive for cytokeratins, smooth muscle actin, vimentin, laminin, collagen type IV, CD8, and CD68." (PMID 19918462, 2009). "Immunohistochemical staining in the tumor cells was positive for CD163, CD68, lysozyme, CD45, and NSE." (PMID 17324277, 2007). "We conducted a complete immunohistochemical analysis of our collective of tumour samples using CD3 (B lymphocytes), CD20 (T lymphocytes) and CD68 (macrophages) antibodies." (PMID 17261184, 2007). "All specimens contained cells positive for CD68, CD163, S100 and CD1a in epithelial tumor tissue and tumor stroma." (PMID 18047662, 2007). "For almost all markers (except CD8, CD68, and PS100), there was a trend towards increased cell infiltration in responsive tumours." (PMID 16404427, 2006). "Flow cytometric analysis of disaggregated tumours showed that there was increased numbers of CD8+ and CD68+ cells in regressing E.G7-OVA tumours when compared to EL-4 tumours and progressive E.G7-OVA tumours." (PMID 12671716, 2003). "Tumour regression was accompanied by increased infiltration of CD8+ T cells, which was nearly double that in EL-4 tumours, and of macrophages (CD68+)." (PMID 12671716, 2003). "The proximity assessment further emphasized the positive relationship between CD68+ macrophages and IgG-stained apoptotic cleaved caspase 3+ tumor cells in GIC-A tumors, but not in GIC-C tumors." (PMID 41510151, 2026). "As expected, the overall number of CD68+CD163− M1-type macrophages were rather low, with 0.9 cells/mm2 tumor near and 1.4 cells/mm2 tumor distant in the stromal compartment and 8.1 cells/mm2 and 6.0 cells/mm2 in the epithelial compartment of samples of the APBI studies." (PMID 40498004, 2025). "CD68 expression has significant negative relation with tumor purity, significant positive correlation with tumor-infiltrating levels of B cell, CD4+ T cell, CD8+ T cell, macrophage, myeloid dendritic cell and cancer associated fibroblast in STAD." (PMID 40918116, 2025). "First, we assessed the expression of CD68 and CD163 in both normal and tumor mucosa." (PMID 41573553, 2025). "The results demonstrated that mCRC patients who benefit more from sintilimab plus anlotinib often exhibit greater infiltration of immune cells, including PD-1+ CD8+ T cells, PD-L1+ CD68+ macrophages, CD20+ B cells, and CD56dim NK cells, into the tumor microenvironment." (PMID 40954146, 2025).
tumor (continued). "Multiplex immunofluorescence analysis revealed that TLR7 was significantly upregulated by IFNα therapy in cells expressing myeloid cell markers such as CD1c+, CD68+ and CD141+ and in XCR1+ cells, a marker specific for type I DCs in the tumor and the surrounding stroma." (PMID 39849091, 2025). "The number of CD68+ cells, including macrophages, increased 24 h after Hematoporphyrin Derivatives-PDT (HpD-PDT) and peaked 48 h after HpD-PDT in a mouse model in which PDT inhibited GBM growth through an anti-tumor response." (PMID 40807266, 2025). "CD68 expression has significant negative relation with tumor purity and significant positive correlation with tumor-infiltrating levels of B cell, CD4+ T cell, CD8+ T cell, macrophage, myeloid dendritic cell and cancer associated fibroblast in LIHC." (PMID 40918116, 2025). "However, we previously showed that myeloid-specific proteins CD14, CD68, and PU-1 are intracellularly expressed in LYVE-1+ tumor vessels, suggesting their full merging with myeloid cells." (PMID 40507286, 2025). "Additionally, a variable proportion of CD68+ macrophages and CD8+ and CD3+ T lymphocytes were observed within the tumor microenvironment (TME)." (PMID 40423041, 2025). "Some genera of the intestinal microbiota are positively correlated with the therapeutic response, especially with CD8+ T cell infiltration, but negatively correlated with the intrinsic drug resistance factors of the tumor (such as UPD, HRD and CD68+ monocyte infiltration)." (PMID 41394818, 2025). "In addition, we measured the distances between CK+ tumor cells and various clusters of CD8+ T cells, CD4+ T cells, or CD68+ TAMs." (PMID 40459946, 2025). "Notably, co-expression analysis of LAMP1 with tumor markers CD74 and CD68 revealed that LAMP1 expression is mainly located within the tumoral area, potentially representing cancer cells, CAFs, and MDSCs." (PMID 40872517, 2025). "Positive staining of PD-L1, CD31 (partial +), CD34, CD68, CD163, vimentin and SMA detected in the tumor tissue, indicating that vascular endothelial cells, TAMs and fibroblasts may participate in the pathogenesis of ENKTL." (PMID 40433378, 2025). "Lymph node invasion (pN). ccRCCs with loco-regional lymph node invasion showed significantly higher percentages of CD68 + cells than tumors without node invasion at the tumor center and periphery." (PMID 39751643, 2025). "Furthermore, in these aggressive tumors, we observed FAP + stromal cells surrounding tumor cells and near CD8 + and CD68 + cells." (PMID 39751643, 2025). "Conversely, the tumor was negative for panCK, CD68, and actin, excluding epithelial, macrophage, and smooth muscle components, respectively." (PMID 40361436, 2025). "Flow cytometry demonstrated increased CD163+ M2 macrophage numbers in the liver PMN and MMN of MC38 tumor-bearing mice, contrasting with CD68+ M1 macrophages which showed no increase." (PMID 40765822, 2025). "Initially, a presumptive diagnosis of a fibrohistiocytic tumor was made based on histological features and immunohistochemical results, which were negative for S-100 and positive for CD68." (PMID 40491616, 2025). "The total level of macrophages (CD68 + ) was similar in both FGF2 high and FGF2 low tumor sites." (PMID 40425576, 2025). "Additionally, macrophage density was higher in tumors with ulceration, and both CD68+ and CD163+ macrophage numbers increased progressively with tumor stage, particularly in advanced stages." (PMID 41007741, 2025). "Ki-67 expression in the interface region showed a negative relationship with CD68+ infiltration in the normal tissue region adjacent to the tumor (Spearman = -0.458; P = 0.042)." (PMID 40469283, 2025). "We also found that higher CD68+ cell levels and higher COX-2 levels in the tumor tissue." (PMID 41431078, 2025). "The osteoclast‐like giant cells were observed in about 30% of the tumor, these were positive for immunohistochemistry with CD68 while negative for HepPar1." (PMID 39953652, 2025).
tumor (continued). "Although with controversy, it has been reported that CD68+ cells and CD163+ M2-like macrophages may have relevance with tumor progression and poor prognosis." (PMID 40539047, 2025). "Immunohistochemical analysis revealed a high number of human CD68+ macrophages infiltrating SW480 and HCT116 tumors of NSG-Quad and MISTRG-6 mice, whereas human tumor-associated macrophages (TAMs) were virtually absent in NSG mice." (PMID 40503011, 2025). "IHC analysis revealed numerous CD68‐positive round or spindle‐shaped macrophages infiltrating the tumour, while the tumour cells exhibited no immunopositivity for Merlin." (PMID 40815185, 2025). "Furthermore, immunofluorescence staining revealed colocalization of VSIG4 with CD68, a recognized marker for macrophages, alongside a marked elevation of VSIG4 expression in tumour tissues." (PMID 40405491, 2025). "In the unique monophasic SS sample with necrosis, CD68+ cells were found in necrotic zones and absent amidst tumor cells." (PMID 41155410, 2025). "Moreover, the CD68+/CD8+ ratio also influence prognosis, indicating the protective role of T cells and the tumor‐promoting function of TAMs." (PMID 41357670, 2025). "In this study, we conducted a preliminary investigation into the distribution of bacterial LPS signals in tumor cells and macrophages, but LPS and CD68 are not specific markers for bacteria and macrophages." (PMID 39660865, 2025). "Uniform manifold approximation and projection (UMAP) demonstrated the expression patterns of Pan-CK (tumor cell marker), CD3 and CD45RO (memory T cell markers), CD20 (B cell marker), CD15 (one of the granulocyte markers), and CD68 and HLA-DR (macrophage markers)." (PMID 40593467, 2025). "Furthermore, in the most aggressive tumors in which these TME cells were abundant, we observed FAP + CAFs surrounding tumor cells (as previously reported with myCAFs in other solid tumors) as well as near CD8 + and CD68 + cells." (PMID 39751643, 2025). "Besides, the infiltration of CCR7+ immune cells into the tumor sites through lymphatic vessels were also identified by immunofluorescent staining, such as CCR7+CD11b+, CCR7+CD68+and CCR7+CD3+ cells." (PMID 40685403, 2025). "Among the population of CD68+ cells, CD206+CD68+ (M2) and CD86+CD68+ (M1) cells accounted for 36.2% and 12.7%, respectively, of the population in tumor-surrounding tissues, whereas they accounted for 13.2% (M2) and 45.3% (M1) of the population in normal tissues." (PMID 41354740, 2025). "The first was a non-epithelial tumor consisting of immature spindle-shaped and stellate plaques that were positive for α-1 antitrypsin and the mesenchymal markers vimentin and CD68 but negative for myogenic, neurogenic, and other markers." (PMID 40755904, 2025). "Immunohistochemically, the tumor cells exhibit variable expression of CD34, SMA, and CD68." (PMID 40282503, 2025). "IHC staining results from 169 GC cases further demonstrated a significant negative correlation between MAEA levels and M2 (CD68/CD206) macrophage infiltration within tumor tissue." (PMID 39990651, 2025). "We not only detected enriched macrophages as CD68+ cells in TD-PCLS compared with healthy PCLS, but also documented the subpopulations of antitumor M1 macrophages (IL8) and tumor-promoting M2 macrophages (ALOX15 or CD206) in TD-PCLS, as to be expected for lung tumor tissue." (PMID 40728884, 2025). "For CD68+, classification was performed by setting thresholds using the CD68+/PanCK+ ratio to differentiate tumor samples into positive or negative categories." (PMID 40558790, 2025). "By analysing IL1β, IL10, IL18, TNF-α, TLR4, GATA3, and CD68 expression in 50% of PCa HHV-infected FFPE with an elevated inflammation index (61.8%/21), we detected hyper-expressed levels of IL1β, IL18, and TNF-α in the tumour microenvironment." (PMID 40430084, 2025). "Similarly, in NSCLC tumour tissues, GMIP shows a strong spatial correlation with the M2 macrophage markers CD163 and CD68." (PMID 40275529, 2025).